ALYREF (Aly/REF export factor)
Diseases named in the same sentence as ALYREF in open-access papers (continued):
Sharing a sentence is not in itself a finding about the gene and the disease.
ovarian carcinoma (7 papers, 2013 to 2026). A malignant neoplasm originating from the surface ovarian epithelium. "ALYREF is upregulated in ovarian cancer and is significantly associated with the poor survival of ovarian cancer patients." (PMID 41326692, 2026). "To elucidate the mechanisms underlying ALYREF-mediated cisplatin resistance in ovarian cancer, we conducted RNA-Seq in shALYREF and shNC A2780/DDP cells, along with m5C-BIS-Seq in A2780/DDP and parental cells." (PMID 41345330, 2025). "Furthermore, we analyzed the ALYREF expression in ovarian cancer through a tissue microarray including 134 ovarian cancer patients and found that ALYREF expression was significantly associated with poor survivals (Fig. EV8G,H)." (PMID 41326692, 2026). "High expression of ALYREF is closely associated with worse prognosis for ovarian cancer patients." (PMID 41326692, 2026). "To examine whether LLPS was involved in ALYREF regulation of PARP10 expression, we constructed GFP-ALYREF and its respective truncated forms in which IDRs were depleted or mutated and transfected the constructs into ovarian cancer cells." (PMID 41326692, 2026). "To explore the role of ALYREF in ovarian cancer, we first analyzed ALYREF expression in ovarian cancer using the GEO database and CSIOVDB database (GSE54388, GSE66957, GSE18520, GSE40595, and GSE10971)." (PMID 41326692, 2026). "We next investigated the effects of overexpressing and knocking down ALYREF (shALY-1 and shALY-2) on the growth and migration of ovarian cancer cell lines, including A2780, OVCAR3, and SKOV3 cells (Fig. EV1D,E)." (PMID 41326692, 2026). "Together, these results demonstrate that ALYREF promotes the proliferation and metastasis of ovarian cancer cells in vivo." (PMID 41326692, 2026). "Using a multi-omics strategy, we identified PARP10 as a critical target of ALYREF in ovarian cancer." (PMID 41326692, 2026). "To further explore the functions of ALYREF in ovarian cancer, we performed immunofluorescence staining for ALYREF in ovarian cancer cells and found that ALYREF formed condensates." (PMID 41326692, 2026). "Increased ALYREF protein expression was also observed in ovarian cancer in the CPTAC database and the Hu ovarian cancer cohort." (PMID 41326692, 2026). "To explore the interaction between ALYREF and m5C-modified RNA in ovarian cancer cells, we performed RIP-seq and RNA-BisSeq." (PMID 41326692, 2026). "In this study, we found that ALYREF regulates global RNA abundance in ovarian cancer cells by binding transcripts in an m5C-dependent manner." (PMID 41326692, 2026). "In this study, we report the function of ALYREF-mediated regulation of PARP10 mRNA stability by LLPS in ovarian cancer." (PMID 41326692, 2026). "We found that ALYREF is abnormally upregulated in ovarian cancer and promotes ovarian cancer growth and migration through its m5C-modification recognition activity." (PMID 41326692, 2026). "ALYREF is elevated in ovarian cancer patient samples, and its depletion reduces ovarian tumorigenesis and metastasis in mice in a m5C-dependent manner." (PMID 41326692, 2026). "To elucidate the functional significance of ALYREF in cisplatin-resistant ovarian cancer, we systematically examined its role in malignant phenotypes." (PMID 41345330, 2025). "Combined with RNA-Seq sequencing data on cisplatin-resistant ovarian cancer cells, we discovered that the methyl-binding protein ALYREF is crucial for the emergence of cisplatin resistance in ovarian cancer." (PMID 41345330, 2025). "In our study, we identified a potential role for ALYREF in platinum resistance through reanalysis of RNA-Seq data from cisplatin-resistant ovarian cancer cell lines and single-cell sequencing data from patient samples." (PMID 41345330, 2025). "Subsequent investigations revealed that ALYREF promotes platinum resistance in ovarian cancer cells by activating the Wnt/β-Catenin pathway via the NSUN2/ALYREF/LGR4 signaling axis." (PMID 41345330, 2025).
ovarian carcinoma (continued). "In this study, we integrated RNA-Seq and single-cell transcriptomic data from cisplatin-resistant ovarian cancer cell lines and patient samples, identifying the m5C reader protein ALYREF as a key regulator of platinum resistance." (PMID 41345330, 2025). "A few previous studies described the expression of ALYREF in certain types of human cancer, including up-regulation in squamous cell carcinoma, ovarian cancer and lung cancer, whereas downregulation was described in skin and testicular cancers." (PMID 35776213, 2022). "RT-qPCR confirmed downregulation of these genes in ovarian cancer cells upon ALYREF knockdown." (PMID 41326692, 2026). "Moreover, high ALYREF expression was significantly associated with poor overall survival (OS), disease-free survival (DFS), and progression-free survival (PFS) in ovarian cancer patients." (PMID 41326692, 2026). "ALYREF was overexpressed in ovarian cancer in the CSIOVDB database (Fig. EV1C)." (PMID 41326692, 2026). "Our findings enrich the mechanistic knowledge of how ALYREF regulates ovarian cancer progression via m5C, which may have significant application for new therapeutic strategies for ovarian cancer and other cancers." (PMID 41326692, 2026). "In this study, we explored the role and potential mechanism of ALYREF in ovarian cancer." (PMID 41326692, 2026). "The correlation between PARP10 and ALYREF RNA expression was analyzed in ovarian cancer tissues." (PMID 41326692, 2026). "Our results showed that ALYREF expression was increased in ovarian cancer." (PMID 41326692, 2026). "This convergence reinforces the hypothesis that ALYREF is crucial in the development of cisplatin resistance in ovarian cancer." (PMID 41345330, 2025). "Therefore, we examined whether ALYREF promoted tumorigenesis in ovarian cancer in an m5C-dependent manner." (PMID 41326692, 2026). "Thus, targeting ALYREF may represent a promising strategy to overcome platinum resistance in ovarian cancer." (PMID 41345330, 2025). "Future research will focus on determining whether targeting ALYREF can reverse platinum resistance and exploring the development of small-molecule inhibitors of ALYREF, with the goal of providing novel therapeutic strategies for drug-resistant ovarian cancer patients." (PMID 41345330, 2025). "This study identified four-DERRG signature (ALYREF, ZC3H13, WTAP, and METTL1) in OC, which was an independent prognostic model for patient stratification, prognostic evaluation, and prediction of response to immunotherapy in ovarian cancer by classifying OC patients into high- and low-risk groups." (PMID 36545327, 2022). "PARP10 or ALYREF knockdown decreased the phosphorylation level of PI3K and AKT in ovarian cancer cells." (PMID 41326692, 2026). "Ovarian cancer cells were transfected with the wild-type ALYREF (ALY-wt) or ALY-mut plasmids, and western blotting verified that both ALYREF proteins were effectively overexpressed in ovarian cancer cells." (PMID 41326692, 2026). "This study uncovers a phase separation-dependent role of 5-methylcytosine (m5C) mRNA modification reader ALYREF (aka ALY, BEF) in promoting ovarian cancer." (PMID 41326692, 2026). "This study uncovers a critical function of the 5-methylcytosine (m5C) RNA modification reader protein ALYREF (also termed, ALY; BEF) in ovarian cancer." (PMID 41326692, 2026). "To investigate the functional relationship between ALYREF and LGR4, we knocked down or overexpressed ALYREF in ovarian cancer cells." (PMID 41345330, 2025). "However, LLPS depletion of ALYREF failed to facilitate ovarian cancer cell proliferation, migration, and metastasis." (PMID 41326692, 2026). "Finally, ALYREF and PARP10 expression correlate with poor prognosis in ovarian cancer patients." (PMID 41326692, 2026).
ovarian carcinoma (continued). "Moreover, in ovarian cancer, ectopic ALYREF expression conferred resistance to DNA‐damaging therapeutic agents such as platinum or poly (ADP‐ribose) polymerase (PARP) inhibitors, indicating that ALYREF is a pivotal factor in regulating anti‐cancer responses." (PMID 39915011, 2025). "However, no research has yet examined the contribution of abnormal ALYREF expression to the development and progression of ovarian cancer, as well as its impact on platinum resistance." (PMID 41345330, 2025).
neuroblastoma (6 papers, 2021 to 2025). Neuroblastoma (NB) is the most common solid, extracranial childhood tumor. "Among neuroblastoma patients, the m5C reader ALYREF forms a nuclear coactivator complex alongside MYCN, thereby prompting USP3 transcription and fostering neuroblastoma tumourigenesis." (PMID 40008496, 2025). "Taken together these data showed that MYCN-induced increases in neuroblastoma cell viability and proliferation were, in part, dependent on ALYREF." (PMID 33767157, 2021). "Here our analyses identify ALYREF, expressed from the most common genetic copy number variation in neuroblastoma, chromosome 17q21-ter gain as a key regulator of MYCN protein turnover." (PMID 33767157, 2021). "We also investigated the phenotypic effect of ALYREF knockdown on several human neuroblastoma cell lines with high ALYREF expression." (PMID 33767157, 2021). "Endogenous knockdown of ALYREF in all neuroblastoma cells was accompanied by a significant decrease in cell viability, as measured by Alamar Blue assay." (PMID 33767157, 2021). "Our in vitro and in vivo data strongly supports the role of ALYREF as a co-driver for oncogenesis in neuroblastoma." (PMID 33767157, 2021). "Genetic suppression of ALYREF expression resulted in reduced neuroblastoma cell proliferation in vitro, and delayed neuroblastoma growth in mice." (PMID 33767157, 2021). "Mechanistic experiments revealed that MYCN was dependent on ALYREF to drive neuroblastoma cell proliferation and the two proteins acted in a positive interconnected regulatory pathway that was essential for sustaining mutual, oncogenic expression levels." (PMID 33767157, 2021). "High ALYREF expression in neuroblastoma tumor tissue had prognostic significance, which was independent of MYCN-amplification, therefore we argue that ALYREF may have MYCN-independent oncogenic effects." (PMID 33767157, 2021). "Knockdown of ALYREF had profound effects on the cancer phenotype in neuroblastoma cells." (PMID 33767157, 2021). "To further examine ALYREF as a transcriptional coactivator for MYCN, we evaluated the effect of ALYREF knockdown on USP3 gene transcription in SHEPMYCN3 neuroblastoma cells, which express MYCN under the control of doxycycline, therefore minimising ALYREF knockdown effects on MYCN stability." (PMID 33767157, 2021). "Thus, ALYREF is a transcriptional target of MYCN in MYCN-amplified neuroblastoma cells." (PMID 33767157, 2021). "ALYREF and MYCN form a transcriptional activator complex, which upregulates USP3 expression, promoting the growth and tumorigenicity of MYCN-amplified neuroblastoma cells." (PMID 37537569, 2023). "In neuroblastoma patients, the m5C reader ALYREF forms a nuclear coactivator complex with MYCN to stimulate USP3 transcription, which promotes the tumorigenesis of neuroblastoma." (PMID 37325635, 2023). "In neuroblastoma, MYCN amplification directly upregulates ALYREF transcription and ALYREF regulates MYCN stability in a forward feedback loop." (PMID 37537569, 2023). "In this study, we describe ALYREF as a key regulator of MYCN turnover and neuroblastoma tumorigenesis." (PMID 33767157, 2021). "ALYREF knockdown in SH-SY5Y and SK-N-AS neuroblastoma cells was accompanied by a significant decrease in cell viability, indicating a possible regulatory relationship between cMYC and ALYREF." (PMID 33767157, 2021). "PLK-1, CDK-1, PIK3CA, ATF4, TEAD4 and ALYREF could enhance MYCN protein stability and sustain MYCN expression in neuroblastoma." (PMID 35820898, 2022). "We saw significant positive correlations between ALYREF and MYCN expression levels, as well as ALYREF copy number, further supporting ALYREF as a key intermediary in the cooperation between 17q21-ter gain and MYCN-amplification in the malignant neuroblastoma phenotype." (PMID 33767157, 2021). "High ALYREF mRNA expression correlated with MYCN mRNA expression in the TARGET25 (n = 154), SEQC29–32 (n = 498), and Kocak34 (n = 476) neuroblastoma patient tumor data sets." (PMID 33767157, 2021).
neuroblastoma (continued). "ALYREF protein expression levels were high in MYCN-amplified and MYCN overexpressing human neuroblastoma cells (lanes 1–7) across a panel of neuroblastoma cell lines, with significantly higher expression levels when compared to human fibroblasts (lanes 12 and 13; WI-38 and MRC5)." (PMID 33767157, 2021). "We next sought evidence that ALYREF mRNA expression in the organ of tumor origin, sympathetic ganglia, correlated with an MYC expression signature from tumor initiation to progression in tissues from the TH-MYCN+/+ transgenic neuroblastoma mouse model." (PMID 33767157, 2021). "Together these data suggest MYCN and ALYREF bind together in a transcriptional coactivator complex to increase USP3 transcript levels, consequently reducing MYCN ubiquitination, and further increasing MYCN protein to the levels required to drive neuroblastoma tumorigenesis." (PMID 33767157, 2021).
liver cancer (5 papers, 2020 to 2024). An epithelial or non-epithelial malignant neoplasm that arises from the liver. "The m5C methyltransferase NSUN4 recognizes protein ALYREF associated with liver cancer outcomes." (PMID 35686101, 2022). "Together, the results confirmed that ALYREF promotes proliferation, migration, and invasion of liver cancer cells in vitro and tumor formation and proliferation in vivo." (PMID 38164181, 2024). "The results demonstrated that ALYREF was dysregulated in tumor tissues compared to normal tissues, including primary liver cancer." (PMID 34367948, 2021). "Through an analysis of an online database and 3 independent LIHC cohorts, we found that ALYREF was markedly elevated in human liver cancer tissues and was significantly correlated with LIHC clinicopathological parameters, including Ki67+ cell rate, high-grade TNM stage, and poor prognosis." (PMID 38164181, 2024). "Notably, the mutation frequencies of NSUN2 in esophagus and stomach cancers, NSUN3 in esophagus cancer, and ALYREF in liver cancer were particularly high." (PMID 33365328, 2020). "Among them, the P value of the NSUN5 and ALYREF genes in colorectal cancer, liver cancer, and GC is less than 0.05, and the NSUN6 gene also has significant differences in colorectal cancer, liver cancer, and PC." (PMID 33365328, 2020).
lung adenocarcinoma (5 papers, 2021 to 2024). A carcinoma that arises from the lung and is characterized by the presence of malignant glandular epithelial cells. "ALYREF has been found to contribute to the malignant phenotype of lung adenocarcinoma (LUAD) by stabilizing YAP33." (PMID 38491127, 2024). "In lung adenocarcinoma patients, ALYREF, together with NSUN2, promotes m5C modification of YAP (Yes-Associated Protein) mRNA in the 3’-UTR, thus increasing the stability of YAP mRNA and causing enhanced exosome secretion, tumor malignancy and drug resistance." (PMID 37325635, 2023). "In lung adenocarcinoma patients, NSUN2 and ALYREF were found to be oncogenic through interacting with YAP mRNA." (PMID 37325635, 2023). "In addition, NSUN2 and ALYREF promoted YAP m5C modification in its 3’-UTR regions, increasing mRNA stability in lung adenocarcinoma." (PMID 38331765, 2024). "Here, we validated that YAP expression was higher in lung adenocarcinoma (LUAD) tissues compared to adjacent normal tissues, and found that YAP m5C modification occurred in its 328–331 3′ UTR region under the promotion NSUN2 and ALYREF, and increased the stability of YAP mRNA." (PMID 36123390, 2023).
lung carcinoma (5 papers, 2022 to 2025). "Data from TCGA database indicate that ALYREF is highly expressed in lung cancer patients and that high ALYREF expression is associated with a poor prognosis." (PMID 40653497, 2025). "The finding that silencing ALYREF increases the nuclear expression of circRREB1 aligns with the elevated expression of ALYREF in lung cancer tissues." (PMID 40653497, 2025). "The results showed that the decrease in EZH2 expression triggered by NOP2 knockdown as well as the antitumor phenotype of lung cancer cells were suppressed by overexpression of ALYREF." (PMID 39013911, 2024). "Here, we found that NOP2 and ALYREF had a co-regulatory role in the stability of EZH2 mRNA in lung cancer." (PMID 39013911, 2024). "We focused on YAP1, as LINC02159 knockdown decreased its gene expression in NSCLC cells and a recent study suggested that ALYREF may regulate YAP1 5-methylcytosine modification to increase its mRNA stability in lung cancer." (PMID 37537569, 2023). "In a word, our research highlights the significant role of NOP2 in LUAD and offers novel mechanistic insights into the NOP2/ALYREF/EZH2 axis, which holds promise as a potential target for lung cancer therapy." (PMID 39013911, 2024). "To verify whether ALYREF is a functional m5C reader in lung cancer cells, we performed RIP assay with ALYREF antibody in H1650 and H1299 cells, and the RT-qPCR results showed that ALYREF could bind to EZH2 mRNA, suggesting that ALYREF might be the m5C reader." (PMID 39013911, 2024). "The roles of ALYREF in NSCLC remain unclear although a recent study suggests that it, together with other m5C/m6A-related genes, could predict prognosis and immunotherapy efficacy in lung cancer." (PMID 37537569, 2023).
oral squamous cell carcinoma (5 papers, 2019 to 2024). "Through the regulation of cellular invasiveness and migration, ALYREF is linked to local lymph node metastasis in human oral squamous cell carcinoma." (PMID 31355144, 2019). "There is a potential link between ALY (Aly/REF export factor), RRP1B, and metastasis in oral squamous cell carcinoma (OSCC)." (PMID 38610928, 2024).
prostate carcinoma (5 papers, 2021 to 2026). A carcinoma that arises from epithelial cells of the prostate gland. "In prostate cancer, ACC1 mRNA in the m5C modified state interacts with ALYREF to enhance its stability and facilitate nuclear export, resulting in lipid accumulation and progression of prostate cancer." (PMID 40809690, 2025). "Additionally, ALYREF inhibition significantly impaired renal and prostate cancer cell proliferation in vitro." (PMID 38361753, 2024). "Notably, ALYREF was involved in multiple pathways, including cell cycle, DNA replication, and prostate cancer-related pathways." (PMID 34325709, 2021). "ALYREF, DNMT1, and TET2 were involved in the cell cycle, DNA replication, and prostate cancer-related pathways." (PMID 34325709, 2021).
colon cancer (3 papers, 2013 to 2024). "ALYREF is thought to be a preventive factor against colon cancer." (PMID 38436027, 2024).